SOX2 (SRY-box transcription factor 2)
Diseases named in the same sentence as SOX2 in open-access papers (continued):
Sharing a sentence is not in itself a finding about the gene and the disease.
colitis (8 papers, 2017 to 2025). Inflammation of the colon. "In 4 month-old mice, YFP + Hu+ double-expressing neurons rose in frequency from 1.1 ± 0.6% of all Hu+ cells in controls to 4.4% ± 1.9% following DSS colitis (p < 0.05), suggesting that colitis causes Sox2+ cells to give rise to new neurons." (PMID 28566702, 2017). "Lgr5 was highly expressed in the TZ in the early stages of colitis, followed by higher expression levels of SOX2." (PMID 39684417, 2024). "Our data show a significant decrease in the stem/progenitor cell compartments of the DG (Gfap+ and Sox2+ cells) in mice with active colitis." (PMID 36232813, 2022). "In a similar fashion, Sox2+ neurons were significantly increased after DSS colitis (0.5 in control and 4.9% after DSS)." (PMID 28566702, 2017). "Patients with colitis of either type had an average of 14% (range 7–19%) Hu+ neurons that co-expressed Sox2, while double-labeled cells were seen only in approximately 2% in control colon." (PMID 28566702, 2017). "ScRNA-seq analysis also revealed that a new skin-like epithelial population called squamous neo-epithelium marked by the expression of Sox2/Krt14/Krt7 could confer the resistance to colitis injury and rebuild the epithelial structure after colitis." (PMID 36045190, 2022). "Indeed, DSS-induced colitis was shown to trigger the transdifferentiation of SOX2+, PLP1+ glial cells to enteric neurons." (PMID 34571902, 2021). "However, following C. rodentium induced colitis, the number of Sox2+ neurons increased significantly both proximally (8.9%) and distally (3.4%)." (PMID 28566702, 2017). "In human colitis, Sox2-expressing neurons increase from 1–2% to an average 14% in colitis." (PMID 28566702, 2017). "Given the increase in Sox2-expressing neurons following colitis in adult animals, we hypothesized that Sox2-expressing cells give rise to neurons." (PMID 28566702, 2017). "Another possible explanation is that a subset of neurons may begin to express Sox2 in humans with colitis." (PMID 28566702, 2017). "Here we present evidence that enteric cells expressing Sox2 and PLP1, markers that label enteric glia in the adult gut, undergo neurogenesis in response to colitis." (PMID 28566702, 2017).
coloboma (8 papers, 2008 to 2024). An abnormality in which a part of a structure in one or both eyes is missing. "In eye genetic disorders (Microphtalmia/Anophtalmia/ Coloboma-Optic Nerve Hypoplasia, MAC-ONH), only between 40 and 50% of cases are explained by mutations within the exomes of several genes, including SOX2, OTX2 and PAX6 among the most frequently mutated." (PMID 35887306, 2022). "Screening of SOX2 was completed in 89 patients with a variety of ocular anomalies, including 28 with A/M and 61 with normal eye size and anterior segment dysgenesis, cataract, isolated coloboma, or other eye disorders." (PMID 20454695, 2010). "Because the forme fruste of coloboma was asymptomatic and genetic testing was negative in both blood and saliva, some of the reported SOX2 de novo and gonadal mosaicism occurrences may indeed have resulted from gonadosomatic mosaicism." (PMID 33719903, 2021).
hypopituitarism (8 papers, 2011 to 2021). A condition of diminution or cessation of secretion of one or more hormones from the anterior pituitary gland. "The pituitary transcription factors HESX1, LHX3, and SOX2 are vital for early patterning of the forebrain and pituitary, and mutations in these developmental genes result in syndromic hypopituitarism with gonadotropin deficiency in humans." (PMID 31220230, 2019). "Sox2 mutations are associated with pituitary hormone deficiencies and the protein is required for pituitary progenitor proliferation, but its function has not been well characterized in this context." (PMID 27226320, 2016). "A review report presented that mutation of several transcription factors, including Sox2 gene, results in congenital hypopituitarism or septo-optic dysplasia in murine neonates." (PMID 25051057, 2014). "Heterozygous SOX2 mutations have been described in patients with hypopituitarism and severe ocular abnormalities." (PMID 21919124, 2011). "HESX1, GLI2, and SOX3 mutations have been linked to hypopituitarism, and mutations in SOX2, LHX3, LHX4, and PROP1 may cause gonadotropin deficiency." (PMID 34948037, 2021). "The pituitary transcription factors LIM Homeobox 3(LHX3), SRY-Box 2 (SOX2) and HESX homeobox 1 (HESX1) are vital for early patterning of the forebrain and pituitary, and mutations in these developmental genes result in syndromic hypopituitarism with gonadotropin deficiency in humans." (PMID 29730183, 2018). "Sox2 null mice are not viable, but Sox2-het are viable and display a moderate reduction in body size and hypopituitarism." (PMID 23217425, 2012).
lymphoma (8 papers, 2015 to 2025). A malignant (clonal) proliferation of B- lymphocytes or T- lymphocytes which involves the lymph nodes, bone marrow and/or extranodal sites. "On the basis of our previous study, the aberrant expression of Sox2 in these lymphoma cells is attributed to the constitutive activation of the NPM-ALK/STAT3 axis, and inhibition of either ALK or STAT3 led to a substantial decrease in Sox2 expression." (PMID 34287231, 2021). "Oxidative stress, namely H2O2 has been demonstrated to promote lymphoma stemness phenotype, through the activation of the wingless (WNT)/β-catenin/MYC/sex determining region Y box 2 (SOX2) axis in the anaplastic lymphoma kinase-positive ALCL." (PMID 32197371, 2020). "Second, we analyzed perturbation signatures of (i) mouse lymphomas with artificially induced MYC overexpression and (ii) knock-out experiments of NANOG, POU5F1 and SOX2 in human embryonic stem cells." (PMID 29741575, 2018). "Second, we analyzed perturbation signatures of artificially induced overexpression of MYC in lymphomas of Eμ-Myc-transgenic mice as well as knock-out experiments of NANOG, POU5F1 and SOX2 in human embryonic stem cells." (PMID 29741575, 2018). "In both AML cell lines, there was no/minimal Sox2 and Oct4 detected compared to SupM2, a lymphoma cell line." (PMID 38203669, 2023). "Second, we analyzed perturbation signatures of (i) mouse lymphomas with artificially induced overexpression of MYC and (ii) knock-out experiments of NANOG, POU5F1 and SOX2 in human embryonic stem cells to examine if the different methods are able to identify the perturbed regulators." (PMID 29741575, 2018).
oligodendroglioma (8 papers, 2013 to 2025). A well-differentiated (WHO grade II), diffusely infiltrating neuroglial tumor, typically located in the cerebral hemispheres. "Our DEGs exhibited only a minimal overlap with the genes previously identified as being regulated by Sox2 in a mouse oligodendroglioma model." (PMID 38891067, 2024). "The C57BL/6 N mice were injected with wild-type oligodendroglioma cells from established mouse model and upon vaccination with SOX2 peptides, significant delay in tumor growth was observed." (PMID 25114775, 2014). "Lastly, a recent publication by Favaro and colleagues proved that SOX2 is required for in vitro CSC maintenance in a high-grade oligodendroglioma mouse model." (PMID 25114775, 2014). "The requirement of SOX2 in oligodendroglioma suggested possible therapeutic intervention." (PMID 25114775, 2014). "This elegant study proved the obligatory function of SOX2 in oligodendroglioma tumor initiation." (PMID 25114775, 2014). "Furthermore, use of SOX2 peptide vaccination in immunodeficient mice transplanted with high-grade oligodendroglioma cells delayed tumour development, increased survival rates, and the combination with chemotherapy drug temozolomide further doubled survival time compared to vehicle controls." (PMID 26580604, 2015). "Oligodendrogliomas exhibit a proneural genetic signature and the OG cells expressed NG2 and PDGFRα; however, they did not express the proneural markers Sox2, CD133, or Olig2 and only expressed low levels of Notch1 and nestin." (PMID 24278309, 2013).
renal carcinoma (8 papers, 2011 to 2025). A carcinoma arising from the epithelium of the renal parenchyma or the renal pelvis. "SOX2 activation in renal cancer is associated with the induction of a stem cell-like phenotype and is a predictor of poor prognosis in RCC." (PMID 37268911, 2023). "Moreover, the attenuated sphere forming ability of IL4-knockdown cells was accompanied by the downregulation of Sox2 and Oct4, which are known as markers of breast and renal cancer stem cells." (PMID 27895317, 2016). "In this study, we cultured 786-O and ACHN renal cancer cells with SFMto increase spherical cells with stem cell characteristics, detected the expressionlevels of CSCs markers, and found that the protein expression levels of CSCs markersCD44, Oct4, and SOX2 increased." (PMID 38985013, 2024). "Especially, the expression of c-MYC, KLF4, OCT4, NANOG and SOX2 implies that these 5 factors are involved in carcinogenesis and progression of RCC, and probably there are RCC cancer stem cells existing in renal carcinoma." (PMID 21982273, 2011). "NANOG, SOX2, and OCT4 (octamer‐binding transcription factor 4) are key regulators of pluripotency and tumor invasion, and they have been proposed as biomarkers for cancer stemness in breast and renal carcinoma." (PMID 34532864, 2021). "Core pluripotency stem cell master regulators (OCT4, SOX2 and NANOG) along with epithelial–mesenchymal transition (EMT) markers (Snail, Slug, vimentin and N-cadherin) were induced in human prostate, breast, lung, bladder, colorectal, and renal cancer cells." (PMID 30742096, 2019). "To investigate if these master regulators could act as a core signature for clinically aggressive cancers, we explored an OCT4/SOX2/NANOG (OSN) expression signature in a large cohort of clinical cancers (n = 884), comprising of prostate (n = 275), bladder (n = 292) and renal cancers (n = 317)." (PMID 30742096, 2019).
schizophrenia (8 papers, 2017 to 2025). A major psychotic disorder characterized by abnormalities in the perception or expression of reality. "We do not find significant differences in the percentages of proteins associated with ID, ASD or schizophrenia between the interactomes of starting transcription factors Tcf4, Olig2, Npas3, Sox2 (P-value >0.2 for all MD categories)." (PMID 28375211, 2017). "At the end of each culture period, NPCs in both control and schizophrenia-derived cells stained positive for neural progenitor markers such as nestin and SOX2 (SRY-Box 2)." (PMID 36451159, 2022). "Control organoids showed organized ventricle zones with SOX2-expressing progenitor cells and MAP2-expressing neuronal cells at the cortical layer, while schizophrenia patients had a larger area covered by SOX2 progenitors, also showing MAP2 distribution throughout the organoid." (PMID 36451159, 2022). "In vivo, we studied the gene expression of DCX, Sox2, BDNF, and NeuN in the SVZ and HIP in an MK-801-induced animal schizophrenia model." (PMID 35887056, 2022). "Sox2 was even more depleted in the MAM model animals than in the controls, and overall, the Sox2 protein was barely detectable in hippocampi of the schizophrenia-like animals (d5)." (PMID 28300292, 2018).
tongue squamous cell carcinoma (8 papers, 2014 to 2023). A squamous cell carcinoma that arises from the tongue. "A recent study reported that EGFR activation induces SOX2 phosphorylation at Y277, inhibiting ubiquitination, and subsequent autophagic degradation of SOX2 in a human tongue SCC cell line." (PMID 35048028, 2021). "A recent meta-analysis identified SOX2 as a promising biomarker for tongue SCC, which is also an HPV-independent SCC." (PMID 33918187, 2021). "SOX2 can modulate cell aggression and motility by affecting the capacity of migration, invasion and proliferation in tongue squamous cell carcinomas." (PMID 31508790, 2019). "SOX2 is important in epithelial cell differentiation and is expressed in basal epithelium of the tongue and in tongue squamous cell carcinoma." (PMID 25531390, 2014). "SOX2 was reported to be a prognostic indicator of tongue squamous cell carcinoma." (PMID 30186173, 2018). "Gefitinib, a selective tyrosine kinase inhibitor of EGFR, induced a reduction in OCT4 and SOX2 levels in CAL‐27 and SCC‐15 cells, two human tongue squamous cell carcinoma cell lines." (PMID 31823521, 2020).
Ataxia (7 papers, 2016 to 2025). Ataxia refers to impaired coordination of voluntary muscle movement. "In addition, mutations in some of these potential targets lead to ataxia and BG defects reminiscent of the ones due to Sox2 loss, for example mutations in the tumor suppressor adenomatous polyposis coli (APC) and in the transcription factor Sox4." (PMID 31540269, 2019). "Conditional knockout of SOX2 in the cerebellum results in vermis hypoplasia and progressive ataxia phenotypes." (PMID 40870030, 2025). "The early Sox2 deletion leads to an expansion of the Otx2-expressing domain into the hindbrain, a reduction of the cerebellar vermis, and ataxia in the mutants." (PMID 35626641, 2022). "Conditional knock-out of Sox2 in the developing cerebellum (mediated by Wnt1-Cre recombinase) results, postnatally, in hypoplasia of the central portion of the cerebellum, the vermis, and ataxia." (PMID 31540269, 2019). "Interestingly, this later Sox2 ablation was accompanied by mild ataxia, while the vermis appeared normal, suggesting a likely direct role of Sox2-expressing BG in regulating neuronal activity." (PMID 31540269, 2019). "These Sox2-creERT2::Ctnnb1(ex3)Fl/+ mice developed a marked failure to thrive until the age of postnatal day P21 with significant deficits in body size and body weight compared to controls and presented with general weakness and ataxia." (PMID 27902722, 2016).
Barrett esophagus (7 papers, 2009 to 2025). Esophageal lesion lined with columnar metaplastic epithelium which is flat or villiform. "SOX2 is a master regulator of upper GI squamous epithelial identity, and its loss is involved in the transcriptional reprogramming seen in Barrett’s esophagus development." (PMID 40587339, 2025). "Since embryonic esophageal epithelium of p63 knockout mice and hypomorphic sox2 mice showed metaplastic changes of morphology and gene expression, we speculate that p63 or sox2 knockout mice may be more susceptible to Barrett's esophagus and esophageal adenocarcinoma after surgery." (PMID 19627616, 2009). "We previously showed that SOX2 is robustly expressed in normal esophageal squamous epithelium and decreases during BE development and esophageal adenocarcinoma progression." (PMID 40587339, 2025). "Compared with esophageal adenocarcinoma, the estimated frequency of SOX2 amplification was reported to be significantly higher in ESCC." (PMID 26465158, 2015). "Thus, SOX2 is critical for foregut squamous epithelial differentiation, and its decreased expression is likely an initiating step in progression to BE and then to esophageal adenocarcinoma." (PMID 40587339, 2025). "By contrast, expression of SOX2 remained suppressed, whereas expression of GATA4 was upregulated in Barrett’s metaplasia, suggesting that Barrett’s metaplasia exhibits a transcription pattern similar to that of primitive transitional epithelial cells." (PMID 33495473, 2021). "In conclusion, our study establishes a role for the transcription factors SOX2 and CDX2 in the progression from gastric to gastrointestinal differentiation in Barrett's metaplasia." (PMID 27766003, 2016). "In conclusion, our study establishes a role for transcription factors SOX2 and CDX2 in the progression from gastric to gastrointestinal differentiation in Barrett's metaplasia." (PMID 27766003, 2016). "A similar interplay and reciprocal expression of CDX2 and SOX2 is observed in the lower esophagus during progression to the metaplastic epithelium of Barrett’s esophagus and adenocarcinoma, despite the lack of involvement of h." (PMID 40149431, 2025). "Here, we sought to characterize SOX2 and CDX2 expression in the distinct morphological steps recognized on the evolutionary phenotype of Barrett's metaplasia and in Barrett's ADC (BA), in an attempt to evaluate their involvement in the differentiation reprogramming of human esophageal mucosa." (PMID 27766003, 2016). "In contrast, van Olphen and colleagues showed that loss of SOX2 is associated with progression to neoplastic lesions in the context of Barrett's metaplasia and that more than 60% of the BA did not express SOX2." (PMID 27766003, 2016).
cholangiocarcinoma (7 papers, 2020 to 2025). A carcinoma that arises from the intrahepatic biliary tree (intrahepatic cholangiocarcinoma) or from the junction, or adjacent to the junction, of the right and left hepatic ducts (hilar cholangiocarcinoma). "This study not only elucidates the complex interplay between LINC00511, YTHDF2, and SOX2 but also proposes potential therapeutic targets within this regulatory axis for cholangiocarcinoma treatment." (PMID 39445001, 2024). "Gli1 is responsible for increased SOX2 expression in cholangiocarcinoma under hypoxia conditions and promotes cancer cell stemness, epithelial-to-mesenchymal transition and invasion." (PMID 33499351, 2021). "Recently, lncRNA SOX2 overlapping transcript (SOX2-OT) was proposed to promote a series of tumors progression such as esophageal squamous cell carcinoma, lung squamous cell carcinoma, and cholangiocarcinoma." (PMID 32528555, 2020). "YAP1 upregulates SOX2 via binding to TEAD on the promoter region of SOX2, ultimately promoting the proliferation of cholangiocarcinoma cells." (PMID 38331879, 2024). "Furthermore, correlation analysis using cholangiocarcinoma datasets from The Cancer Genome Atlas (TCGA-CHOL) showed that WNT pathway genes (AXIN2, CTNNB1, LEF1) positively correlated with TIC signature genes (KIT, SALL4, CD44, SOX2)." (PMID 39774471, 2025). "A time‐course following treatment with actinomycin D showed that siRNA‐mediated knockdown of YTHDF2 specifically reduced the stability of SOX2 mRNA in CCLP‐1 cells with little effect on HIBEC, thus indicating a CCA‐specific dependency where YTHDF2 supports cholangiocarcinoma cells." (PMID 39445001, 2024).
colorectal tumor (7 papers, 2009 to 2023). "Similarly, elevated levels of endogenous SOX2 in colorectal tumor cells are associated with slower proliferation, but higher tumor-initiating capacity, than the SOX2low population of colorectal tumor cells." (PMID 32998722, 2020). "Perhaps consistent with the requirement for Sox2 in goblet cell differentiation, Sox2 activated a Muc5AC-luciferase reporter in colorectal tumors, and Muc5B mRNA was increased in lung when Sox2 was overexpressed in a transgenic mouse model." (PMID 20011520, 2009). "Additionally, colorectal tumor cells that endogenously express higher levels of SOX2 proliferate more slowly, exhibit higher chemoresistance, and possess a higher tumor-initiating capacity than the SOX2low tumor cell population." (PMID 32998722, 2020). "For example, knockdown of SOX2 in colorectal tumor cells induced mesenchymal-epithelial transition." (PMID 28388544, 2017). "Moreover, knockdown of SOX2 decreased the growth rate of cultivated colorectal tumour cell lines in vitro and in vivo." (PMID 22168803, 2011). "Mechanistically, it might therefore be assumed that both β-catenin and SOX2 drive the malignant progression of CCs by inducing cancer stemness of colorectal tumour cells." (PMID 22168803, 2011). "Although the 5-FU treatment could effectively inhibit colorectal tumor growth, we observed an enrichment of CSCs in 5-FU-treated tumors supported by the upregulation of CSC markers (CD44, SOX2), which could be responsible for the observed chemoresistance." (PMID 36827121, 2023).